SNORD115-44 (small nucleolar RNA, C/D box 115-44)
Synonyms: HBII-52-44
Gene: Small nucleolar RNA gene on chromosome 15 (25,250,859 to 25,250,940, forward strand). Ensembl gene ENSG00000202261.
Gene Ontology:
Biological process: RNA processing
Cellular component: nucleolus
Homologues: Orthologues: dog SNORD115 (63% identical). Paralogues in human: SNORD115-11 (99% identical), SNORD115-29 (99% identical), SNORD115-36 (99% identical), SNORD115-43 (99% identical), SNORD115-12 (98% identical), SNORD115-16 (98% identical), SNORD115-22 (98% identical), SNORD115-26 (98% identical), SNORD115-33 (98% identical), SNORD115-39 (98% identical), SNORD115-6 (98% identical), SNORD115-9 (98% identical), and 37 more.